CXCR4 (C-X-C motif chemokine receptor 4)
Diseases named in the same sentence as CXCR4 in open-access papers (continued):
Sharing a sentence is not in itself a finding about the gene and the disease.
esophageal cancer (41 papers, 2006 to 2025). A primary or metastatic malignant neoplasm involving the esophagus. "In primary esophageal cancer, overexpression of CXCR4 was found to be associated with clinicopathological features e.g. gender, histological differentiation, tumor depth, and status of lymph node metastasis, and poor prognosis." (PMID 33579381, 2021). "We previously identified HER2 and CXCR4 as possible alternative targets in the treatment of esophageal carcinoma and associated mild hypoxia leading to expression of CAIX with increased metastatic spread." (PMID 34065626, 2021). "Expression of CXCR4 correlates significantly with overall and tumor-specific survival in esophageal carcinoma and is associated with poor prognosis." (PMID 23082154, 2012). "The chemokine receptor CXCR4 has been implicated in metastatic dissemination of various tumors and correlates with poor survival in esophageal carcinoma." (PMID 23082154, 2012). "While clinical evidence suggested that continuous up-regulation of CXCL12/CXCR4 was significantly associated with poor prognosis in patients with esophageal cancer, but the role and mechanism of CXCL12/CXCR4 in the invasion and metastasis of esophageal cancer has not been reported by far." (PMID 28193907, 2017). "Importantly, we have already previously shown that CXCR4-expression in a similar patient collective (136 patients) was associated with poor clinical outcome in esophageal cancer patients." (PMID 23082154, 2012). "In addition, chemokine receptor (CXCR4) was also associated with cancer cell survival, proliferation, chemotaxis, migration, and adhesion, and significantly correlated with lymph node metastasis in esophageal cancer." (PMID 24130695, 2013). "Data on the role of CXCR4 expression in esophageal cancer progression, and the prognosis of patients after RCHT are presently limited." (PMID 35993091, 2022). "In vitro CXCR4 expression has been shown to correlate with advanced stage, poor differentiation and worse survival in oesophageal cancer." (PMID 36140541, 2022). "miR-302b suppresses tumor growth and transcription factors protein expression through targeting erb-b2 receptor tyrosine kinase 4 (ERBB4), interferon regulatory factor 2 (IRF2), and Cxc chemokin receptor 4 (CXCR4) in esophageal cancer." (PMID 33729388, 2021). "As previously discussed, the CXCR4 inhibition with AMD3100 leads to a significant reduction of esophageal cancer growth and metastases." (PMID 32998713, 2020). "In human esophageal cancer, CXCR4 overexpression promoted cell invasion in vitro and tumor growth in vivo and indicated worse survival outcome." (PMID 32232002, 2020). "Reference 26 to “Kaifi, J.T.; Yekebas, E.F.; Schurr, P.; Obonyo, D.; Wachowiak, R.; Busch, P.; Heinecke, A.; Pantel, K.; Izbicki, J.R., Tumor-cell homing to lymph nodes and bone marrow and CXCR4 expression in esophageal cancer." (PMID 31146450, 2019). "Kaifi, J.T.; Yekebas, E.F.; Schurr, P.; Obonyo, D.; Wachowiak, R.; Busch, P.; Heinecke, A.; Pantel, K.; Izbicki, J.R., Tumor-cell homing to lymph nodes and bone marrow and CXCR4 expression in esophageal cancer." (PMID 31146450, 2019). "The aberrant CXCR4 levels in the nucleus and/or cytoplasm have been described in lung, breast, ovary, gastric, and esophageal cancers." (PMID 30760238, 2019). "Overall, the outcomes of this study implicate that Snail-1 knockdown utilizing siRNA can significantly interrupt esophageal cancer cell migration and reduce metastatic-related factors, vimentin, CXCR4, MMP-9, and induce miR-34a and let-7a in vitro." (PMID 30276140, 2018). "Three further groups were treated with trastuzumab, an antibody against HER2, as well as AMD3100 and CTCE9908, two inhibitors of CXCR4 that have been shown to be involved in migration and tumour cell homing in esophageal carcinoma." (PMID 29865880, 2018).
esophageal cancer (continued). "Evidences including the important role of CXCL12/CXCR4 in tumor invasion and metastasis and its strong correlation with the poor prognosis in patients with esophageal cancer have been reported in literature." (PMID 28193907, 2017). "The results showed significantly high expression of CXCR4 in both OE33 cells derived or esophageal cancer tissues derived ECSCs." (PMID 28193907, 2017). "The anti-migratory activities and suppressive effects on metastasis-related factors such as HER2, MMP2, MMP9, TM4SF3, CXCR4 of the absorbed AP components were revealed in esophageal cancer cells EC-109." (PMID 28405006, 2017). "A recently published study of our group has immunohistochemically analyzed the CXCR4 expression of esophageal cancer specimen on conventional histological slides." (PMID 24074251, 2013). "In esophageal cancer, TGF-β, MMP-1, and CXCR4 were upregulated and associated with cancer progression." (PMID 24130695, 2013). "The chemokine CXCL12 and its receptor CXCR4 play a major role in tumor invasion, proliferation and metastasis in different malignant diseases, including esophageal carcinoma, amongst others." (PMID 24074251, 2013). "The positive correlation between HER2- and CXCR4-expression was validated in esophageal cancer patients." (PMID 23082154, 2012). "We show here for the first time that a positive correlation of HER2- and CXCR4-expression exists in esophageal carcinomas of patients." (PMID 23082154, 2012). "The chemokine CXCR4 has been suggested to play an essential role in tumor cell homing to lymph nodes and bone marrow in esophageal carcinoma." (PMID 23082154, 2012). "In esophageal carcinoma it has been shown that CXCR4 is involved in metastases to lymph nodes and bone marrow and, moreover, is associated with a poor clinical prognosis." (PMID 23082154, 2012). "The aim of this study was to investigate a correlation between the expression levels of HER2 and CXCR4 and to evaluate the involvemnent of CXCR4-expression in HER2-positive esophageal carcinoma." (PMID 23082154, 2012). "The reduction of metastases strengthens the assumption that CXCR4 is indeed involved in metastastic homing in esophageal carcinoma." (PMID 23082154, 2012). "CXCR4 expression was detected in both types of esophageal cancer – squamous cell and adenocarcinoma." (PMID 17176471, 2006). "The aim of our study was to evaluate the role of CXCR4 in tumor spread of esophageal cancer with a differentiated view of the two predominant histologic types – squamous cell and adenocarcinoma." (PMID 17176471, 2006). "Expression of the chemokine receptor CXCR4 in esophageal cancer is of major relevance in both histologic entities – squamous cell and adenocarcinoma." (PMID 17176471, 2006). "Probably CXCR4 expression can be expected in more than 50% of esophageal cancer patients." (PMID 33579381, 2021). "We hypothesize that additional PET/CT imaging with Pentixafor to visualize the chemokine receptor CXCR4 is feasible in both newly diagnosed and pretreated recurrent esophageal cancer and gives complementary information to FDG PET/CT." (PMID 33579381, 2021). "Most importantly, the ability of esophageal cancer stem cells to spread and metastasize could be inhibited by blockage of CXCR4 with inhibitors or shRNA approaches both in vivo and in vitro studies." (PMID 28193907, 2017). "RNAi targeting CXCR4 is known to inhibit proliferation and invasion of esophageal carcinoma cells." (PMID 25047112, 2014). "The clinical relevance of HER2- and CXCR4-expression was examined in esophageal carcinoma patients." (PMID 23082154, 2012). "The aim of this study was to investigate the effects of single and combined inhibition of HER2 and CXCR4 receptor pathways, and to examine HER2- and CXCR4-expression levels under inhibition in order to determine a possible involvement of CXCR4-expression in HER2-positive esophageal carcinoma." (PMID 23082154, 2012).
esophageal cancer (continued). "Besides determining the importance of the presence of HER2 and CXCR4 in a representative patient collective, a highly metastatic model of esophageal carcinoma was used for evaluation." (PMID 23082154, 2012). "It has been shown that CXCR4 may have a prognostic value when expressed in certain tumors such as esophageal cancer." (PMID 18001467, 2007). "Inhibition of esophageal cancer progression by CXCR4 antagonists might be a promising therapeutic option in the future." (PMID 17176471, 2006). "Thus, the exact biological functions of CXCR4 in terms of tumor dissemination of esophageal cancer is yet undetermined." (PMID 17176471, 2006). "The interaction between esophageal cancer-expressed CXCR4 and SDF-1α may be a key event in directing malignant cells to these "homing organs", and this mechanism may also account for metastasis from other organs, as previously reported." (PMID 17176471, 2006). "In this study, we found that autocrine CXCL12/CXCR4 was one of the major mechanisms underlying the metastatic property of ECSCs through ERK1/2 signaling pathway, and might serve as a therapeutic target in esophageal cancer patients." (PMID 28193907, 2017). "This blockade led to reduced expression of IL-19-regulated genes such as TGF-β, Matrix Metalloproteinase-1 (MMP-1), CXCR4, and Cyclin B (CCNB1), highlighting the therapeutic potential of IL-19 inhibition in esophageal cancer." (PMID 40806452, 2025). "Oesophageal cancer stem cells (CSCs) secrete SDF‐1 and express CXCR4, which promotes the formation of an autocrine signalling loop, serving as a system to maintain the invasive, metastatic, and stem‐like properties of these CSCs." (PMID 39855896, 2025). "This study demonstrated that CXCR4 and ERK1/2 activation enhanced esophageal cancer cell line migration and invasion in transwell and Matrigel models, which was blocked by antagonists of both proteins or CXCR4 silencing." (PMID 36118530, 2022). "Recently, increasing number of publications focusing on contributive roles of the CXC chemokine receptor 4 (CXCR4) on growth and cell cycle of OSCC and esophageal carcinoma using PI3/Akt were reported." (PMID 29381751, 2018). "Mechanistically, we demonstrated that CXCL12/CXCR4 activated the ERK1/2 pathway and thereby ultimately maintained the characteristics of high-level invasion and metastasis of esophageal cancer stem cells." (PMID 28193907, 2017). "Taken together, our findings suggested that autocrine CXCL12/CXCR4 was one of the major mechanisms underlying the metastatic property of esophageal cancer stem cells through ERK1/2 signaling pathway, and might serve as a therapeutic target for esophageal cancer patients." (PMID 28193907, 2017). "This study found that esophageal cancer stem cells not only autocrine a great amount of CXCL12, but also high expression of its corresponding receptor CXCR4." (PMID 28193907, 2017). "Moreover, CXCL12-CXCR4 interactions were shown to stimulate the autocrine secretion of CXCL12 and induce cancer invasion and metastasis in CXCR4-positive esophageal cancers." (PMID 37760498, 2023). "The knockdown of chemokine CXCL12 also inhibited the expression of EMT-related proteins and the mesenchymal morphology changes of esophageal cancer cells, but the knockdown of C-X-C motif chemokine receptor 4 (CXCR4) had no such effect." (PMID 35264069, 2022). "We further sorted out ECSCs and non-ECSCs from OE33 cells and samples of esophageal cancer tissues by flow sorting, and determined the expression of CXCR4 by quantitative PCR." (PMID 28193907, 2017). "Our results suggest an important role of CXCR4, a possible regulation of HER2 though inhibition of the CXCR4 pathway and a subsequent regulation of local tumor progression and metastatic homing of esophageal carcinoma." (PMID 23082154, 2012). "However, further functional analysis will be necessary to investigate the interaction of CXCR4 and HER2 pathways in esophageal carcinoma." (PMID 23082154, 2012).
esophageal cancer (continued). "The correlation of CXCR4- and HER2-expression and the elevation of HER2-expression and reduction of metastases through CXCR4-inhibition suggest a possible functional linkage and a role in tumor dissemination in HER2-positive esophageal carcinoma." (PMID 23082154, 2012). "However, it should be highlighted that CXCR4 expression is not specific for esophageal cancer." (PMID 33579381, 2021). "MIF serves as a non-cognate ligand for CXCR2 and CXCR4: MIF (and CXCR4) in the TME are adverse prognostic indicators in esophageal cancer, and it can induce CXCR ligand and regulators of macrophage infiltration like CD44." (PMID 26267609, 2015).
ischemia (41 papers, 2010 to 2024). A hypoperfusion of the BLOOD through an organ or tissue caused by a PATHOLOGIC CONSTRICTION or obstruction of its BLOOD VESSELS, or an absence of BLOOD CIRCULATION. "CXCR4 blockade is associated with an impaired incorporation of EPC into sites of ischemia-induced neovascularization and disturbed restoration of blood flow to ischemic limbs, suggesting that CXCR4 is important for therapeutic integration of EPC into the vascular bed." (PMID 21655289, 2011). "Activation of the CXCL12/CXCR4/ACKR3 axis is known to aid myocardial repair through ischemia-triggered hypoxia-inducible factor-1α (HIF-1α)." (PMID 38994928, 2024). "HIF-1α is a crucial transcription factor in the cardiovascular system, as it regulates gene expression of the CXCL12/CXCR4/ACKR3 axis during ischemia." (PMID 38994928, 2024). "This means that inflammation is the anti-tumor immune effect of CXCR4-axis Tregs due to ischemia, and to our knowledge, ours is the first report of this association in the area of conjunctival SCC." (PMID 35358193, 2022). "Administration of CXCR4+ bone marrow mononuclear cells (BMMNCs) sorted by magnetic beads significantly enhanced the perfusion recovery in mice after hindlimb ischemia compared to CXCR4− BMMNCs." (PMID 36051532, 2022). "This evidence does not only prove that BMSC exosomes can promote the angiogenesis in brain tissues after ischemia but also indicates that CXCR4 can improve this effect." (PMID 33381162, 2020). "The chemokine receptor CXCR4 belongs to the large family of G protein-coupled receptors, and EPCs incubated with CXCR4 antibodies or EPCs from CXCR4+/− mice displayed an impaired incorporation of EPCs into the sites of ischemia-induced neovascularization." (PMID 31964421, 2020). "In support of our results, adenovirus-mediated over-expression of CXCR4 in rat hearts before myocardial ischaemia-reperfusion has been shown to significantly increase infarct size 24 h later, accompanied by cardiomyocyte apoptosis and worse cardiac function." (PMID 30738798, 2019). "The increase of SDF-1 expression in response to a hypoxic environment, such as ischemia, acts as a cellular signal to attract CXCR4+ stem cells, which are potentially beneficial to cardiac repair." (PMID 29784000, 2018). "Taken together, these data suggest a role for exosomal CXCR4 interaction with SDF-1α in the targeting of exosomes to kidney endothelium after ischemia." (PMID 30397255, 2018). "Stromal cell-derived factor-1 (SDF-1) and its corresponding receptor CXCR4 have been shown to play prominent roles during cardiovascular development, cardiac repair, and tissue homeostasis after ischemia." (PMID 28550361, 2017). "CXCL12 is the single natural ligand for the chemokine receptor CXCR4 and the CXCL12/CXCR4 axis is important in the mobilization, migration and recruitment of EPCs to sites of ischemia." (PMID 27834814, 2016). "Atorvastatin and rosuvastatin treatments increased the numbers of CXCR4-positive EPCs in the blood and recruited to the ischemia tissues." (PMID 26309120, 2015). "The present investigation demonstrates that treatment with the CXCR4 antagonist AMD3100 in mice subjected to permanent focal ischemia enhances long-term recovery of lost neurological function." (PMID 25881123, 2015). "In animal studies, we analyzed the effects of atorvastatin or rosuvastatin treatments in recovery of capillary density and blood flow, the expression of vWF and CXCR4 at ischemia sites in hindlimb ischemia ICR mice." (PMID 26309120, 2015). "In conclusion, our study indicates that VEGFR1-TK signaling plays a critical role in the recovery from ischemia by being involved in the mobilization of hematopoietic cells expressing CXCR4+VEGFR1+ from BM." (PMID 26133989, 2015). "Brain stem cells expressing the CXCR4 cytokine receptor migrate into areas of inflammation and ischemia in response to the chemoattractant thrombin and the anaphylotoxins C3a and C5a." (PMID 21152121, 2010).